IKZF1 (IKAROS family zinc finger 1)
Diseases named in the same sentence as IKZF1 in open-access papers (continued):
Sharing a sentence is not in itself a finding about the gene and the disease.
B-cell acute lymphoblastic leukemia (16 papers, 2012 to 2026). A neoplasm of lymphoblasts committed to the B-cell lineage, typically composed of small to medium-sized blast cells. "Deletions within IKZF1 in B-cell acute lymphoblastic leukemia (B-ALL) lead to a loss of normal IKAROS function, conferring leukemic stem cell properties, including self-renewal and subsequent uncontrolled growth." (PMID 38255194, 2024). "The first IKZF1 mutations that were linked to human pathologies were somatic and associated with a worse prognosis in B-cell acute lymphoblastic leukemia (B-ALL)." (PMID 35566429, 2022). "Mutations or deletions of IKZF1 have shown to have a poor prognosis in precursor B-cell acute lymphoblastic leukemia (B-ALL)." (PMID 32085659, 2020). "Earlier reports have described somatic IKZF1 pathogenic variants in the context of high-risk B-cell acute lymphoblastic leukemia (B-ALL) development, but more recently our understanding of the IKZF1-linked spectrum of diseases has expanded to include several IEI arising from germline IKZF1 variants." (PMID 36359748, 2022). "The hematopoietic transcription factor Ikaros (IKZF1) regulates normal B cell development and functions as a tumor suppressor in precursor B cell acute lymphoblastic leukemia (B-ALL)." (PMID 36278683, 2022). "Some of these features are concordant with those seen in patients with other IGH-rearranged B-cell acute lymphoblastic leukemias: young age at onset, male sex, low blast count, high incidence of IKZF1 deletion and intermediate prognosis." (PMID 31921638, 2019). "Interrogate the impact of IKZF1 deletion on therapy-outcomes of adults with common B-cell acute lymphoblastic leukemia." (PMID 27067989, 2016).
systemic lupus erythematosus (16 papers, 2011 to 2026). An autoimmune multi-organ disease typically associated with vasculopathy and autoantibody production. "In current study, we showed evidence for gene–gene interaction between the 2 independent lupus-associated SNPs within the IRF5 and IKZF1 (AP = 0.41, RERI = 0.93)." (PMID 23236436, 2012). "Interestingly, this study identified other transcription factors, including other members of the Ikaros family (IKZF1 and IKZF3), among the candidate predisposition genes for lupus." (PMID 38203623, 2023). "Thus, in a cohort of 117 paediatric lupus cases (<16 y, median age 9 y) in which 20% had familial SLE, drawn from Europe, Asia and Africa, a diagnostic yield of 7% (eight moFL cases) were identified (C1QA, C1QC, C2, DNAS1L3, IKZF1)." (PMID 40465409, 2025). "Three members, IKZF1 (IKAROS) (rs2366293-C, rs4917014-T), IKZF3 (AIOLOS) (rs2941509-T), and IKZF2 (HELIOS) (rs6435760-C) have been implicated in systemic lupus erythematosus (SLE)." (PMID 38885295, 2024). "IKZF1, HLA–DQ2A/B, and BACH2 genetic loci that affect IgG glycome composition show pleiotropy with systemic lupus erythematosus (SLE), indicating a potentially causative role of aberrant IgG glycosylation in SLE." (PMID 26200652, 2015).
colorectal cancer (14 papers, 2015 to 2023). A primary or metastatic malignant neoplasm that affects the colon or rectum. "Colorectal cancer brain metastasis whole exome sequencing and whole genome sequencing data analysis showed that colorectal cancer brain metastasis mutation related genes (including IKZF1) are related to homologous recombination defects (HRD) feature." (PMID 35414773, 2022). "In addition to clinical trials involving hepatocellular carcinoma, the value of BCAT1 as a diagnostic marker was recently tested in patients with colorectal cancer, alongside the ikaros family zinc finger 1 (IKZF1) gene." (PMID 29211698, 2018). "Differently methylated regions within markers such as BCAT1, SEPT9 and IKZF1 have previously been shown to have ignorable levels of methylation in WBCs and high levels in colonoscopy-confirmed patients with colorectal cancer." (PMID 37438612, 2023). "The biomarkers used for the proof-of-principle analysis, DNA methylation of BCAT1 and IKZF1, have previously been used to detect recurrence of colorectal cancer in plasma samples." (PMID 37710283, 2023). "In support of this idea, IKZF1 mutations elevates mutational signatures of homologous recombination deficiency (HRD) and mismatch repair deficiency (MMRD) in colorectal cancer." (PMID 35414773, 2022). "Cell-free circulating tumour-derived DNA (ctDNA) can be detected by testing for methylated BCAT1 and IKZF1 DNA, which has proven sensitivity for colorectal cancer (CRC)." (PMID 29796114, 2018). "For a number of cancers it has been possible to identify particular genes that are methylated with high frequency, e.g., GSTP1 in prostate cancer, SHOX2 in lung cancer, SEPT9, NRDG4, RASSF1A, THBD, BCAT1 and IKZF1 in colorectal cancer (CRC)." (PMID 27983717, 2016). "Specific genes, such as BCAT1 and IKZF1, are methylated with high frequency in colorectal cancer (CRC) tissue compared to normal colon tissue specimens." (PMID 26445409, 2015). "Interestingly, we found that four of the markers best suited to distinguish cases from controls in our study were the already well-known colorectal cancer markers IKZF1, SFRP1, SFRP2 and VIM." (PMID 37438612, 2023). "Studies have shown that genetic mutations in IKZF1 are associated with poor prognosis in hematologic tumors and colorectal tumors; Low expression of DOCK2 is associated with a poor prognosis in colorectal cancer and lung cancer patients." (PMID 36311703, 2022). "The DNA methylation level of two biomarkers used for the detection of recurrence of colorectal cancer, BCAT1 and IKZF1, was analyzed using ddPCR with the 4Plex assay for normalization." (PMID 37710283, 2023). "A similar sensitivity was observed in this study, with methylation of BCAT1 and/or IKZF1 detected in plasma from 6/10 (60%) stage IV patients, demonstrating the successful use of the combination of CNA and EpiTect kits for detection of these biomarkers in blood from colorectal cancer patients." (PMID 37710283, 2023). "DMRs residing in four genes, BCAT1, GRASP, IKZF1 and IRF4, exhibited low positivity, 3.5% to 7%, in the plasma of colonoscopy-confirmed healthy subjects, with the sensitivity for detection of ctDNA in colonoscopy-confirmed patients with colorectal cancer being 65%, 54.5%, 67.6% and 59% respectively." (PMID 27983717, 2016).
Autoimmunity (12 papers, 2017 to 2026). The occurrence of an immune reaction against the organism's own cells or tissues. "To explore the impact of alternative splicing of IKZF1 on the function of mature T cells and the risk of autoimmunity, we generated a panel of human T-cell clones with truncating mutations in IKZF1 exons 4, 6, or both." (PMID 41677588, 2026). "Our results suggest that even modest alterations of IKZF1 splicing can have significant effects on gene expression and function in mature T cells, potentially contributing to autoimmunity in susceptible individuals." (PMID 41677588, 2026). "IKZF1 variants were associated with lymphoblastic cell deficiency, autoimmunity and the development of malignancies, including hematological diseases, particularly acute leukemia (AL)." (PMID 36834692, 2023). "The directionality of our genetic epidemiological results was consistent with this biological background: the G allele of our meta-analysis lead SNP rs10230978 which was associated with elevated IKZF1 expression was protective for ovarian cancer while increasing autoimmunity (type 1 diabetes) risk." (PMID 40428397, 2025). "IKAROS, encoded by IKZF1, is a master transcription factor of lymphopoiesis, but the mechanisms by which it causes autoimmunity are unknown." (PMID 38885295, 2024). "In addition to these associations, several loss-of-function (LOF) IKZF1 variants have been described that cause immunodeficiency and autoimmunity." (PMID 38885295, 2024). "Coding mutations in IKZF1 in humans are a cause of common variable immune deficiency (CVID) and autoimmunity." (PMID 38655862, 2024). "Here, we report the mechanisms of how IKZF1 and UBR4 variants in a case of familial IgG4-RD cause autoimmunity with a dominant bias for Th2 polarization." (PMID 38885295, 2024). "While Ikzf1-Treg-cko mice do not develop spontaneous autoimmunity, Ikaros-deficient Treg are unable to control conventional T cell-mediated immune pathology in response to TCR and inflammatory stimuli in models of IBD and organ transplantation." (PMID 38655862, 2024). "Although somatic hypermutation can contribute to both gain and loss of self-reactivity and autoimmunity may be caused by both follicular and extrafollicular pathways, molecular defects (i.e., DNASE1L3 and IKZF1 deficiency) have been shown to drive extrafollicular SLE." (PMID 34889940, 2022). "The lack of spontaneous inflammation or autoimmunity in Ikzf1-fl-Foxp3-Cre mice is similar to mice with Treg-specific deletion of Prdm1, Icos, Il10 and Mef2d." (PMID 38655862, 2024). "We observed no clear signs of frank autoimmunity in aged (1-year-old) Ikzf1-fl-Foxp3-YFP-Cre mice." (PMID 38655862, 2024).
B-cell precursor acute lymphoblastic leukemia (10 papers, 2013 to 2025). "The IKZF1 gene, which encodes the Ikaros transcription factor, is frequently deleted or mutated in patients with B-cell precursor acute lymphoblastic leukemias that express oncogenes, like BCR-ABL, which activate the JAK-STAT5 pathway." (PMID 33180866, 2020). "Similarly, deletions on 7p12 of IKZF1 gene (which encodes the transcription factor Ikaros) are associated with a very poor outcome and high relapse rate in B-cell acute lymphocytic leukemia." (PMID 23641812, 2013). "IKZF1 deletion (ΔIKZF1) is an important predictor of relapse in childhood B-cell precursor acute lymphoblastic leukemia." (PMID 27419633, 2016).
melanoma (9 papers, 2019 to 2024). A malignant, usually aggressive tumor composed of atypical, neoplastic melanocytes. "Overexpression of IKZF1 in melanomas enhanced the recruitment of immune infiltration and sensitivity to PD1 and CTLA4 inhibitors." (PMID 32850314, 2020). "In melanoma, IKZF1 was identified as a key driver of immature TLS formation." (PMID 38469550, 2024). "However, we found pathological mutations in the PTPN11, NF1, CUX1, IKZF1 gene and TERT promoter, which better fit a diagnosis of a melanoma than of lung cancer." (PMID 34819052, 2021). "IKZF1 did not affect melanoma cell proliferation, but its overexpression significantly inhibited TLS maturation." (PMID 38469550, 2024). "Together, these results indicate that highly expressed IKZF1–3 gain clinical significance for predicting the prognosis of patients with SKCM, IKZF3 is an independent prognostic factor of SKCM, thus suggesting that IKZF3 are prognostic biomarkers and immunotherapeutic targets of melanoma." (PMID 36353107, 2022). "The relationship between IKZF1 and melanoma is not yet well established." (PMID 30709382, 2019). "Consistent with our findings with breast cancer cells, depletion of IKZF1 or lenalidomide treatment greatly reduced the number of CTCs produced from footpad-injected B16F10 cells without affecting the growth of the primary melanoma." (PMID 36991428, 2023).
hypogammaglobulinemia (8 papers, 2016 to 2024). "B cell lymphopenia, hypogammaglobulinemia, and recurrent infections are highly penetrant clinical features of most patients with IKZF1 mutations." (PMID 37273190, 2023). "IKAROS Family Zinc Finger 1 (IKZF1 or IKAROS) heterozygous mutation present with hypogammaglobulinemia and progressive B cell deficiency." (PMID 36756122, 2023). "Recently, individuals with B lymphopenia, agammaglobulinemia, and recurrent sinopulmonary infections due to mutations in TCF3, SPI1, PAX5, IKZF1, or IKZF3 have been reported." (PMID 37273190, 2023).
breast carcinoma (6 papers, 2013 to 2024). "In breast cancer, the application of ginseng polysaccharides can inhibit the proliferation of MDA-MB-231 cells by activating IKZF1." (PMID 36353107, 2022). "In breast cancer, the application of ginseng polysaccharide was able to suppress MDA-MB-231 cell proliferation by the activation of IKZF1." (PMID 34950704, 2021).
chronic myeloid leukemia (6 papers, 2012 to 2024). "In chronic myeloid leukemia, deletions and mutations of IKZF1 have been described upon progression to predominantly lymphoid blast crisis." (PMID 37833543, 2023). "Deletion of a single IKZF1 allele or mutations of a single copy of IKZF1 were firstly detected in 15 % of all cases of pediatric B-cell ALL and in more than 80 % of Ph+lymphoid leukemia cases, either de novo Ph+ ALL or chronic myeloid leukemia at progression to lymphoid blast crisis." (PMID 22528731, 2012).
common variable immunodeficiency (6 papers, 2021 to 2025). "Germline IKZF1 mutations have been described in families with common variable immunodeficiency (CVID) and in cases of familial and sporadic ALL." (PMID 35294722, 2022). "Although IKZF1 mutations are found in common variable immunodeficiency (CVID), there have been at least two reports of patients with IKZF1 LoF variants developing SLE." (PMID 38420886, 2024).
myeloid malignancies (6 papers, 2017 to 2023). "This may yield a novel therapeutic approach in myeloid neoplasms based on IKZF1 mutation status." (PMID 37833543, 2023). "In addition to lymphoid malignancies, we have found that IKZF1-mediated signaling pathways also mediate the anti-tumor activity of lenalidomide in myeloid malignancies." (PMID 34680233, 2021).
acute leukemia (5 papers, 2014 to 2024). A clonal (malignant) hematopoietic disorder with an acute onset, affecting the bone marrow and the peripheral blood. "For instance, we found that IKZF1 and CEBPe variants were associated with a low risk of early-age acute leukemia compared with previous international studies." (PMID 37416530, 2023). "Two common polymorphisms in the IKZF1 gene (rs4132601 and rs11978267 variants) have been reported to be associated with childhood acute leukemia (AL) risk, however the results were inconsistent." (PMID 25423013, 2014). "Thus, the association between IKZF1 polymorphisms and childhood acute leukemia in different populations need to be validated by further studies with large sample size." (PMID 25423013, 2014). "However, several following replication studies could not validatethe association between polymorphisms (rs4132601 and rs11978267) in IKZF1 gene and acute leukemia risk." (PMID 25423013, 2014). "Casein kinase 2 (CK2) inhibition restores transcriptional repression of the PI3K pathway, as well as genes important for cell cycle progression, in IKZF1-deleted acute leukemia." (PMID 38255194, 2024). "In this review, we make a brief overview of the physiological role of IKAROS and the molecular pathway that contributes to acute leukemia pathogenesis through IKZF1 gene lesions." (PMID 36834692, 2023). "Thus, variants in the IKZF1 gene maybe associated with increased risk of childhood acute leukemia." (PMID 25423013, 2014).
combined immunodeficiency (5 papers, 2021 to 2025). A broad classification of inherited disorders presenting at birth that affect both the cell-mediated and humoral aspects of the immune response. "Of note, newborns with IKZF1 variants have been detected through severly reduced T-cell receptor excision circles (TREC) in newborn screening with severe combined immunodeficiency (SCID)-like phenotypes." (PMID 38813543, 2024). "In addition, it was previously reported that a case of IKZF1-related early-onset combined immunodeficiency was missed by TREC-based SCID screening but was identified when the patient’s KREC levels were determined." (PMID 38540372, 2024).
Down syndrome (5 papers, 2013 to 2024). "Expression quantitative trait locus analysis in non-Down syndrome lymphoblastoid cell lines has demonstrated an association between the rs4132601 risk allele and decreased IKZF1 mRNA levels." (PMID 33411777, 2021). "In comparison to CRLF2neg patients, higher number of CRLF2pos patients were associated with Down syndrome (4/29 vs. 3/357, p=0.002) and IKZF1 deletions (10/29 vs. 55/357, p=0.02)." (PMID 29899835, 2018). "CRISPR/Cas9-mediated deletion of the region encompassing the rs17133807 major allele (r2 with rs58923657 = 0.97) resulted in significant reduction of IKZF1 mRNA levels in lymphoblastoid cell lines, with a greater effect in Down syndrome versus non-Down syndrome cells." (PMID 33411777, 2021).
myelodysplastic syndrome (5 papers, 2016 to 2025). A clonal hematopoietic disorder characterized by dysplasia and ineffective hematopoiesis in one or more of the hematopoietic cell lines. "With this functional modulation, LEN significantly downregulates IKZF1/3 and exerts its therapeutic action on the patients of MM and 5q-deletion myelodysplastic syndrome (5q-MDS)." (PMID 38344143, 2023). "Promoter region analysis and chromatin immunoprecipitation-sequencing (ChiP-seq) revealed that GPR68 contained binding peaks for Ikaros family zinc finger 1 (IKZF1); IKZF1 functions as a transcriptional repressor of GPR68 in a myelodysplastic syndrome (MDS) cell line." (PMID 30696114, 2019).
Pancytopenia (5 papers, 2016 to 2025). An abnormal reduction in numbers of all blood cell types (red blood cells, white blood cells, and platelets). "Supporting this, it has been reported that a child with a constitutional, de novo heterozygous point variant in the IKZF1 gene exhibited congenital pancytopenia similar to the hematopoietic abnormalities seen in the IKZF1-null mouse model." (PMID 36834692, 2023). "However, a recent paper describes 29 individuals from six families with heterozygous IKZF1 mutations and a predominant phenotype of low serum immunoglobulin and progressive B cell loss without overt pancytopenia." (PMID 27755182, 2016).
primary immunodeficiencies (5 papers, 2019 to 2024). "Germline IKZF1 single-nucleotide variants and deletions have been linked to primary immunodeficiencies." (PMID 38885295, 2024). "IKAROS/IKZF1 mutations have been previously associated with different forms of primary immunodeficiency." (PMID 34694366, 2021).
T-cell acute lymphoblastic leukemia (5 papers, 2021 to 2025). Acute lymphoblastic leukemia of T-cell origin. "While we did not investigate the mechanism by which Pom alters the PI3K pathway in PELs, it likely involves IKZF1, which has been shown to suppress PI3K pathway in T-cell acute lymphoblastic leukemia cells." (PMID 33411730, 2021).
T-cell leukemia (5 papers, 2015 to 2025). A malignant disease of the T-lymphocytes in the bone marrow, thymus, and/or blood. "Interestingly, IMiDs-driven downregulation of IKZF1/IKZF3 is rather non-toxic to T-cells or T-cell leukemias but results in increased expression of interleukin 2 (IL-2) and decreased expression of tumor necrosis factor alpha (TNF-α) in monocytes." (PMID 31487824, 2019).
T-cell lymphoma (5 papers, 2014 to 2025). "Currently, the role of IKZF1/3 degraders, especially cellular modulator of immune recognition (CELMoD), is being explored beyond MM, particularly in B-cell lymphomas and some T-cell lymphomas." (PMID 39500878, 2024). "To identify a tag that could efficiently knock down mouse PD-1, we connected various degron tags to the C-terminus of PD-1, including IKZF1/3, Sall4, ZFP91, and SD, and generated Jurkat human T cell lymphoma cell lines that stably expressed the mouse PD-1-degron tag." (PMID 40687785, 2025).
Thrombocytopenia (5 papers, 2023 to 2025). A reduction in the number of circulating thrombocytes. "The clinical phenotype of IKZF1-mutated AML was dominated by anemia and thrombocytopenia." (PMID 37833543, 2023).
type 1 diabetes (5 papers, 2013 to 2025). "IKZF1 is a candidate pathogenic gene for type 1 diabetes, which is related to its susceptibility." (PMID 35937822, 2022).
adenoma (4 papers, 2014 to 2025). A neoplasm arising from the epithelium. "Although methylated markers such as RASSF1A, SDC2, BCAT1, IKZF1, ALX4, SDC2 and WIF-1, among others, have demonstrated some usefulness for the detection of established cancers, the goal of detecting precancerous adenomas has not been achieved yet." (PMID 32605302, 2020).